INS (insulin)
Diseases named in the same sentence as INS in open-access papers (continued):
Sharing a sentence is not in itself a finding about the gene and the disease.
Hyperglycemia (continued). "In hyperglycemia, AIR is attenuated or even lost because of a decrease in release-competent insulin granules and a disturbance in exocytosis pathways." (PMID 30581872, 2018). "At the 17th week, BPA animals showed fasting hyperglycemia, increased NEFA and insulin levels, and a tendency to be glucose intolerant, which was severely impaired at the 28th week in STD." (PMID 30429829, 2018). "Because insulin promotes glucose uptake in the cellular environment, individuals with T1DM suffer from hyperglycemia." (PMID 29796316, 2018). "ZnT8 knockout (ZnT8KO) mice shows increased hepatic insulin clearance (HIC) which was assessed by the C-peptide to insulin ratio, and postprandial hyperglycemia." (PMID 29791512, 2018). "CuB ameliorated hyperglycemia by activating intestinal AMPK levels and by inducing plasma GLP-1 and insulin release in diabetic mice." (PMID 30298009, 2018). "However, in our study this association between hyperglycaemia and hypoinsulinaemia could not be demonstrated, because in the majority of the samples the serum insulin concentration was below the detection limit of the analysing method." (PMID 29743097, 2018). "Insulin treatment rescued the deep layer vessel growth (Fig EV1F), further confirming that hyperglycemia induced retinal vascular abnormality." (PMID 29180355, 2018). "While hyperglycemia in adulthood may explain some of the structural and functional effects, it does not negate the significance of our results in the context of ELGAN population who are also at increased risk for metabolic disease including impaired insulin sensitivity as adults." (PMID 29544513, 2018). "We assessed the effects of intensive insulin treatment (IIT) on glutathione synthesis rate and redox balance in cancer patients, who had developed stress hyperglycemia after major surgery." (PMID 29300728, 2018). "We induced hyperglycaemia in rats via streptozotocin (STZ) treatment that, with low-dose insulin treatment, was stable and sustained over at least 7 weeks, with little weight loss in the animals." (PMID 29930087, 2018). "At 4-week of intervention with OGLF, the untreated diabetic control group maintained severe hyperglycaemia in the presence of 61.7% serum insulin, 17.3% pancreatic β-cell function (HOMA-β) and 51.5% Insulin sensitivity." (PMID 29019956, 2017). "Hyperglycemia decreases Kir6.2 mRNA levels in rat pancreatic islets as well as in INS-1 cells and reduces Ca2+ influx and insulin secretion from HIT-T15 cells." (PMID 28788070, 2017). "Consistent with the adiposity phenotypes, at 30 weeks‐of‐age, B6 mice fed the HF were hyperglycemic under fasted conditions, glucose intolerant, and insulin resistant; however, it is evident that B6 mice fed a STD also showed signs of fasted hyperglycemia." (PMID 28400497, 2017). "The LADA patients showed an increased hyperglycemia frequency perception compared with the T2DM and T1DM groups, which was mainly at the expense of the insulin-treated LADA group." (PMID 29062603, 2017). "In this regard, more recent studies on the zinc-rich insulin producing islet β-cells suggest a role for MT-3 in streptozotocin (STZ)-induced islet cell death and consequent hyperglycemia." (PMID 28538697, 2017). "STS or insulin administration following Rapa and Dexa prevented hyperglycemia and protected mice from DXR toxicity, suggesting that the hyperglycemia induced by Dexa or Rapa is responsible for the sensitization of mice to DXR-induced chemotoxicity." (PMID 28358805, 2017). "In contrast, an increase of hyperglycemia after CSII initiation was observed, which was more significant in the group receiving long-acting insulin." (PMID 28484424, 2017). "However, whether involving direct effects of insulin, influences of acutely reduced glucose (or overt hypoglycemia) following chronic hyperglycemia, or the fact insulin-treated patients often exhibit greater comorbidities and suffer more protracted disease, awaits further clarification." (PMID 29202762, 2017).
Hyperglycemia (continued). "The insulin-treated LADA patients had a higher hyperglycemia frequency perception than the T1DM (p = 0.04) and insulin-treated T2DM subjects (p = 0.05)." (PMID 29062603, 2017). "Hyperglycemia is defined as chronically elevated fasting blood glucose (FBG) >6.1 mmol/L that typically results from abnormal glucose metabolism and impaired insulin sensitivity." (PMID 28338639, 2017). "Genes consistently altered in both in BBDR.lyp/lyp before versus after the onset of hyperglycemia and in BBDR.lyp/lyp post-hyperglycemia versus to BBDR.lyp/+ and BBDR.+/+ that are regulated by insulin and/or glucose." (PMID 28192442, 2017). "Our results are potentially important for providing a possible mechanism by which INS resistance can be caused directly by hyperglycemia, without obviating or disproving other pathways that may also contribute to insulin resistance, such as those reviewed in the Introduction." (PMID 29207492, 2017). "Next, to investigate the role of ORAIP in hyperglycemia-induced pancreatic β-cell injury, first, we examined the expression of ORAIP by double immunostaining for ORAIP and insulin." (PMID 29057797, 2017). "The correlation coefficients between baseline BMI and follow-up insulin differed significantly between race, MetS, T2DM and hyperglycemia groups." (PMID 28230104, 2017). "The inhibition of insulin signaling pathway via TNF-α lead to suppression of the regulatory enzymes of fatty acids and glucose capture producing hyperglycemia." (PMID 28505155, 2017). "Our results demonstrate that hSeP treatment lowered insulin levels in both the blood and the pancreas, and that AE2 administration ameliorated hSeP-mediated hyperglycaemia and decrease in insulin levels." (PMID 29162828, 2017). "Dipeptidyl peptidase-4 (DPP-4) inhibitors and sodium–glucose co-transporter 2 (SGLT2) inhibitors improve hyperglycemia, and the usefulness of co-administration of DPP-4 inhibitors and insulin therapy has been well established." (PMID 28725273, 2017). "To understand physiologic mechanisms for protection from hyperglycemia after 40 weeks of HFD, we measured 4 h-food restricted and 18 h-fasted blood glucose and insulin levels." (PMID 29107293, 2017). "The study design cannot show causality, does not assess mechanisms by which relative hyperglycemia could confer a poorer prognosis and does not distinguish whether spontaneous normalization of glucose or insulin treatment underlies a relationship between relative hypoglycemia and a complicated AMI." (PMID 29233143, 2017). "Chronic hyperglycemia activates FAM3B expression and couples the secretion of FAM3B and insulin under conditions of insulin resistance." (PMID 28536423, 2017). "We combined perfusion fMRI, time-resolved sampling of glucose, insulin and C-peptide concentrations and a data-driven analysis techniques to study the pattern of CBF change during the transition from fasting glycemia to hyperglycemia." (PMID 28261040, 2017). "The down-regulation of the insulin-signalling pathway could prove beneficial in the long run, as this would protect the pancreas from overproducing insulin and preserve insulin sensitivity in the related target organs, thereby preventing hyperinsulinaemia and hyperglycaemia." (PMID 27795741, 2016). "However, persistent hyperglycemia is very common when surgical stress is imposed upon diabetic patients, sometimes even in normal patients, since the secretion of catecholamine would aggravate insulin resistance, thus reducing the efficacy of exogenous insulin infusion." (PMID 27656261, 2016). "Most of the individuals with confirmed death due to hyperglycaemia were treated with GLD (n = 268, 83%) and almost three quarters (n = 232, 72%) had a history of insulin treatment." (PMID 27768720, 2016). "LBPS strongly enhanced insulin secretion in diabetic rats and it indicates the protective activities of LBPS on β-cell damages in hyperglycaemia." (PMID 27200371, 2016).
Hyperglycemia (continued). "Analysis of insulin and amylin DMIs in individual NOD mice revealed a high degree of variability in DMI values prior to or during the presentation of hyperglycemia." (PMID 27111653, 2016). "Insulin therapy reduced the levels of glucose, ALT, and AST in the mice with STZ-induced hyperglycemia." (PMID 27464894, 2016). "Continuous subcutaneous insulin infusion (CSII) and multiple daily insulin injections (MDI), established therapies for type 1 diabetes, are thought to prevent hyperglycaemia and deleterious glucose fluctuations." (PMID 26649320, 2016). "Consistent with severe hyperglycemia, pancreatic islets obtained from STZ-treated animals exhibited a dramatic reduction in insulin immuoreactive β-cell number, compared to controls." (PMID 26813148, 2016). "Due to decreased insulin response in sensitive tissues combined with excess glucose accumulation, EMS leads to chronic hyperglycaemia and hyperinsulinaemia." (PMID 27629697, 2016). "Individuals in the VFA, VFA with hyperglycemia, VFA with dyslipidemia and VFA with metabolic disease groups all had significantly higher BMI, height, weight, waist circumference, insulin levels, HOMA-IR scores and lower HDL-c values." (PMID 26102277, 2015). "This metabolic change minimizes insulin uptake at the BBB, which is altered by hyperglycemia, leading to uncontrolled food intake." (PMID 26262991, 2015). "Transgenic mice overexpressing human ENPP1 in muscle and liver tissue exhibited elevation in glucose and insulin levels compared to wild-type, conveying that ENPP1 plays a role in insulin resistance and hyperglycemia." (PMID 25825681, 2015). "The mainstay insulin replacement therapy does not parallel normal insulin kinetics and fails to restore normoglycemia in most T1D patients, who experience an increased risk of hypoglycemia, failure to control postprandial hyperglycemia and unpredictable diurnal glucose fluctuations." (PMID 26020954, 2015). "In this study, STZ-induced neuropathic pain signs, hyperglycemia, sciatic nerve histopathological and MDA level changes were improved following insulin treatment." (PMID 26468467, 2015). "Also, we have assessed their association with glucose homeostasis and whether the impaired expression of the targeted PKC isoforms is a primary defect or rather secondary to hyperglycaemia by normalizing plasma glucose levels in the GK rats through insulin treatment." (PMID 26398746, 2015). "Consistent with less extreme hyperglycemia, ZDF rats also have intact native insulin production, while STZ rats are hypoinsulinemic." (PMID 25996498, 2015). "The hallmarks of lowered insulin sensitivity, including hyperinsulinemia, hyperglycemia, and increased HOMA-IR were also manifested 1-week after HFHS dieting, indicative of a rapid response of the animals in attenuating insulin signaling." (PMID 25658428, 2015). "The hyperglycaemia that result from HGL diets can also lead to an increase in the PI3K-to-MAPK ratio, through inhibition of the phosphatidylinositol 3-kinase (PI3K) insulin signalling pathway or the stimulation of the MAPK pathway." (PMID 25774201, 2015). "In the liver, inactivation of hepatic SOCS3 resulted in increased insulin sensitivity and lipogenesis, whereas expression of recombinant STAT3 in the liver markedly attenuated hyperglycemia and hyperinsulinemia in diabetic mice." (PMID 25658428, 2015). "According to our results and previous published studies, we think that hyperglycemia initially occurred due to an increase in intestinal glucose absorption when TAC was administrated, and sustained hyperglycemia led to increased insulin secretion." (PMID 26599323, 2015). "Adding the level of hyperglycaemia before the OGTT, it is possible that the β cells were acting towards the top of their secretory capacity during the OGTT, secreting the insulin available." (PMID 26567860, 2015).
Hyperglycemia (continued). "Insulin-resistant humans have GLUT2 in a permanently apical location, which favours blood-to-lumen glucose flux during fasting hyperglycaemia and remarkably high GU from the lumen after a sugar-rich meal." (PMID 25631620, 2015). "Compared to women, men had higher BMI, WC, WHR, BP, PG, TG, insulin levels, HOMA-IR, and more smokers, hypertension, hyperglycemia and dyslipidemia, but lower HDL-C level, fat mass and BF%." (PMID 25960779, 2015). "Since GLUT4 is the primary transporter responsible for glucose uptake into insulin-sensitive tissues such as muscle and fat, reduced levels of GLUT4 likely contributes to the hyperglycemia and metabolic dysfunction observed in the KO." (PMID 26047815, 2015). "Postprandial hyperglycemia has been recognized as an early defect in patients with T2DM and is due, primarily, to impaired insulin secretion or insulin resistance, as well as environmental factors such as diet and exercise." (PMID 25906471, 2015). "To evaluate their association with glucose homeostasis, we treated GK rats with insulin to normalize their plasma glucose levels and, thus, find out whether the altered gene expression, if detected, in pancreatic islets and liver of GK rats is a primary defect or secondary to hyperglycaemia." (PMID 26398746, 2015). "Toxic effects of hyperglycemia, toxicity of TAC, and excessive secretion by β-cells due to insulin resistance, all contributed to impairment of β-cell function, which eventually lead to hypoinsulinemia." (PMID 26599323, 2015). "The physical exercise prevents hyperglycemia through multiple mechanisms, and the GTT primarily measures pancreatic insulin secretion in response to glucose." (PMID 25531651, 2014). "Indeed, mainly the total deletion of eNOS gene (the partial deletion had a minor effect) was associated with increased circulating insulin levels in the basal state and during the glucose tolerance test, in the absence of basal hyperglycemia or glucose intolerance." (PMID 25093405, 2014). "MET is an oral antidiabetic drug (OAD) that reduces hyperglycemia in patients with T2DM by inhibiting hepatic glucose production (i.e., by improving hepatic insulin sensitivity) and by slowing glucose absorption from the gut." (PMID 24524730, 2014). "We have shown that asiatic acid reduced FBG, serum insulin, AUC of glucose tolerance as well as HOMAR-IR score, indicating that asiatic acid improved insulin sensitivity and hyperglycemia in HCHF diet-induced MS rats." (PMID 24441717, 2014). "Specifically, our data indicate that large reductions in rapid-acting insulin dose administered before and also after intensive running exercise may cause post-exercise hyperglycaemia, but this strategy does not augment ketonaemia in patients with type 1 diabetes." (PMID 24858952, 2014). "Hyperglycemia induces activation of the c-Jun N-terminal kinase (JNK) pathway, which suppresses insulin gene expression and reduces DNA binding of pancreatic and duodenal homeobox factor (PDX)-1." (PMID 24422903, 2014). "In βV59M-RFP mice exposed to chronic hyperglycaemia for 4 weeks, 7% of RFP+ cells (that is, cells of β-cell lineage) contained both insulin and glucagon, and 8% expressed glucagon alone." (PMID 25145789, 2014). "Several carbohydrate metabolism genes involved in metabolism of monosaccharide and carbohydrate and hyperglycemia (e.g. CPT1A, GALK1, INS, LEPR, PRLR and SCD) are highly expressed in mouse CPE and only lowly in human CPE." (PMID 24391755, 2013). "At P6, after 3 consecutive days of hyperglycemia, STZ injection resulted in a significant decrease in circulating insulin in STZ animals when compared to control group (0.32+/−0.07; n = 10 vs 0.17+/−0.01; n = 15, unpaired t-test, p = 0.02)." (PMID 24278148, 2013). "The circulating insulin levels were lower, whereas the FFA and C-peptide levels were higher during hyperglycemia than during normoglycemia." (PMID 23308171, 2013).
Hyperglycemia (continued). "Data from other targets suggest that hyperglycemia-induced TNFα can activate SOCS3, leading to impaired insulin signaling." (PMID 23592917, 2013). "Glucose intolerance and impaired insulin secretion were demonstrated in the male SDT rats at 14 weeks, followed by hyperglycemia and glucosuria at 5 months of age." (PMID 24286086, 2013). "However, as xylazine-induced hyperglycemia observed in the present study was conducted in fasted monkeys which had reduced glycogen stores, the contribution of glycogenolysis to the hyperglycemia was very unlikely, especially in fasted insulin-dependent diabetic monkeys." (PMID 24138083, 2013). "The insulin constructs TA1 and TA4 in adenovirus were tested for their ability to correct hyperglycemia in STZ-treated diabetic rats." (PMID 23826312, 2013). "The blood glucose and insulin levels were estimated to understand if the role of curcumin in cataract onset and progression is due to reduction of STZ-induced hyperglycemia." (PMID 24155984, 2013). "Normal insulin transduction occurs once insulin binds the insulin receptor→IRS-1→Akt pathway and is reduced after exposure to hyperglycemia." (PMID 23592917, 2013). "Since there is significant cross-talk between leptin receptor, insulin, and IGF1R/IGF1 (insulin-like growth factor) signaling pathways, we assessed the effect of hyperglycemia on key intermediates within each of these pathways." (PMID 24260287, 2013). "In a recent study we observed that insulin acutely increases MYCL content and alters cardiac function in the presence of standardized hyperglycemia/hyperinsulinemia (clamp test) in healthy subjects." (PMID 23226508, 2012). "Insulin suppresses HGP by both direct and indirect means, which then mitigates fasting hyperglycemia, impaired glucose tolerance, and postprandial hyperglycemia." (PMID 22590537, 2012). "Therefore, it is significant that the EC extract could potentiate insulin secretion at higher glucose concentration, which could be useful in situations where chronic hyperglycemia decreases the sensitivity of β-islet cells to glucose-induced insulin secretion." (PMID 22645628, 2012). "Therefore, a lack of insulin leads to a failure of regulation of glucose homeostasis and causes the main symptom of diabetes mellitus, a persisting increased concentration of blood sugar ‐ in technical terms hyperglycemia." (PMID 23164557, 2012). "Hyperglycemia upregulated mRNA levels of fibronectin, laminin β1, collagen IVα3, and vascular endothelial growth factor (VEGF), and this increase was prevented by insulin therapy." (PMID 22511849, 2012). "Remarkably, systemic bi-shRNAmousePDX-1 and shRNAmousePDX-1 lipoplexes result in temporal hyperglycemia, representing a predictable off-target effect on mouse islets, since PDX-1 is the predominant regulator of insulin expression." (PMID 22905092, 2012). "GIP as well as GLP-1 is a strong insulinotropic agent, and it has recently been reported that the two incretins have different effects on the insulin secretion, with GIP appearing to be more effective at normoglycemic levels and GLP-1 during hyperglycemia." (PMID 22647249, 2012). "In the present study, insulin secretion following stimulation with glucose, glucose with GIP or GLP-1 and arginine was determined before the onset of hyperglycemia in 10-day-old animals." (PMID 21818396, 2011). "Intravenously administered hyperglycaemia, followed by first arginine, then GLP-1, resulted in an insulin response of the same magnitude in TS and controls." (PMID 21406078, 2011). "There are three key defects in the onset of hyperglycemia in T2DM: increased hepatic glucose production, diminished insulin secretion and impaired insulin action." (PMID 21276212, 2011). "One child experienced severe hyperglycemia (glucose of greater than 20 mmol/L) after PICU admission, was treated with insulin, and was excluded from further analysis after admission." (PMID 21276273, 2011).